FAP (fibroblast activation protein alpha)
Diseases named in the same sentence as FAP in open-access papers (continued):
Sharing a sentence is not in itself a finding about the gene and the disease.
cancer (continued). "For example, the pancreatic stellate cells (PSCs), the FAP+ resident cells of the pancreas, have been implicated in cancer-related fibrosis, induction of PAAD migration, and invasion via the activation of CXCL1-mediated AKT phosphorylation." (PMID 36263225, 2022). "Fibroblast activation protein (FAP)–expressing cancer-associated fibroblasts confer treatment resistance and promote metastasis and immunosuppression." (PMID 34740953, 2022). "The remodeling involves a particular increase in a cancer-associated fibroblast subtype, i.e., FAP+ fibroblasts, and a decrease in a mesenchymal stem-like cell subtype, i.e., NT5E+ fibroblasts." (PMID 35365629, 2022). "Sections were stained for FAPα (Fibroblast associated protein alpha), a marker of cancer-associated fibroblasts (CAFs)." (PMID 35740561, 2022). "Fibroblast activation protein (FAP), which has high expression in cancer-associated fibroblasts of epithelial cancers, can be used as a theranostic target." (PMID 34537893, 2022). "Fibroblast‐activating protein (FAP) is expressed in cancer‐associated fibroblasts (CAFs) in many human carcinomas and in some types of carcinoma cells." (PMID 35818720, 2022). "A subset of TAFs expressing fibroblast associated protein (FAP) have been documented to cause T-cell exclusion from cancer cell nests in multiple cancer models." (PMID 35814453, 2022). "FAP is a dimeric protease localized primarily on the cell surfaces of cancer-associated fibroblasts (CAFs), which have been shown to play a protumoral role." (PMID 36230765, 2022). "Fibroblast activation protein-alpha (FAP-α) is a type 2 transmembrane protein that is an important surface marker of cancer-associated fibroblasts that promotes cancer progression, cancer cell migration, invasion, and colony formation." (PMID 35054034, 2022). "The membrane-associated protease fibroblast activation protein (FAP) is upregulated in the stroma of a large variety of cancers and in inflammatory conditions such as liver cirrhosis and both cardiovascular and rheumatoid diseases." (PMID 35163938, 2022). "While POSTN (Periostin) associates with epithelial–mesenchymal transitions in cancer and the differentiation of mesenchyme, FAP controls fibroblast growth or epithelial–mesenchymal interactions during development, tissue repair, and epithelial carcinogenesis." (PMID 35742914, 2022). "Analysis of the relationship between FAP expression and clinical characteristics displayed that the elevated level of FAP expression was linked to a more advanced cancer stage in STAD." (PMID 35359436, 2022). "A marker protein of cancer-associated fibroblasts is fibroblast activation protein (FAP), a type II transmembrane cell surface serine proteinase belonging to the dipeptidyl peptidase family." (PMID 34168013, 2022). "FAP, a cell membrane-bound type II serine protease, is overexpressed by cancer-associated fibroblasts (CAFs) which are associated with cancer-promoting processes and poor prognosis." (PMID 34342669, 2022). "Fibroblast activation protein (FAP), selectively expressed by cancer-associated fibroblasts (CAFs) in tumor stroma, is considered an interesting target for the detection and treatment of malignant tumors with theranostic tracers." (PMID 35471681, 2022). "FAP-CAR T-cells are against fibroblast activation protein (FAP) expressing cancer-associated stromal cells." (PMID 36569859, 2022). "In contrast, cancer-associated fibroblasts (CAFs) express FAP, which cleave proteins at any post-proline bond in the amino acid sequence." (PMID 35631416, 2022). "The expression of FAP in normal tissue is highly restricted, but this protein becomes overactive in the tumor stroma, which comprises many cancer-associated fibroblasts." (PMID 33777814, 2021). "The expression of cancer-associated FAP in a broad spectrum of cancers offers an optimal target for various molecular-based FAP inhibitor imaging and therapies." (PMID 34959613, 2021).
cancer (continued). "Clusters 0, 1, 2, 3, 4, 5, and 6 show expression of classical cancer-associated fibroblast (CAF) markers (FAP, PDGFRA, LOX, and metalloproteinases)." (PMID 34921143, 2021). "Fibroblast activation protein (FAP) is closely associated with the invasion and metastasis of human cancers and has been revealed as a promising theranostic target for tumors." (PMID 33777814, 2021). "Previous studies reported that FAP was highly expressed in the cancer associated fibroblasts (CAFs), which in turn mediated cancer invasion and metastasis through the degradation of extracellular matrix." (PMID 34335301, 2021). "FAP expression on the cell surface of cancer-associated fibroblasts in both primary lesions as well as lymph nodes metastases was confirmed in all samples." (PMID 34050405, 2021). "Targeting components of the TME like FAP is an emerging pan-cancer diagnostic and therapeutic strategy." (PMID 34226953, 2021). "The basis for FAP-based detection of PM is presumably related to the generally high amount of FAP-positive cancer-associated fibroblasts (CAFs) in these lesions." (PMID 33816304, 2021). "Targeting fibroblast activation protein (FAP) in cancer-associated fibroblasts (CAFs) has attracted significant attention in nuclear medicine." (PMID 34830898, 2021). "The same consideration holds for the FAP antigen that is consistently expressed on activated cancer-associated fibroblasts." (PMID 34484225, 2021). "FAP is overexpressed in cancer-associated fibroblasts (CAFs), which are found in most epithelial tumors." (PMID 34638433, 2021). "Fibroblast activation protein (FAP) is a surface marker of cancer‐associated stromal cells (CASCs), and has a role in remodelling ECM." (PMID 34585512, 2021). "The proline-specific serine protease fibroblast activation protein (FAP) can participate in the progression of malignant tumors and represents a potential diagnostic and therapeutic target." (PMID 33494271, 2021). "Typically, FAP is highly expressed in cancer-associated fibroblasts (CAFs) in 90% of all epithelial tumors, whereas its expression is low to undetectable in most healthy adult tissues." (PMID 33996747, 2021). "Fibroblast activating protein (FAP) has become an important target for cancer diagnostic imaging and targeted radiotherapy." (PMID 35071007, 2021). "The most abundant stromal populations of the three tumors included in the experiment were endothelial cells (PDGFRβ+), fibroblasts (CD56+ cells), and cancer-associated fibroblasts expressing αSMA and FAPα." (PMID 33670410, 2021). "Fibroblast activation protein-α (FAP) is a transmembrane peptidase and a surrogate marker for cancer-associated fibroblasts (CAFs)." (PMID 34525114, 2021). "Fibroblast activation protein (FAP) is overexpressed in cancer-associated fibroblasts (CAFs) in several tumor entities, especially in breast, colon, and pancreatic carcinomas." (PMID 33483880, 2021). "FAP-targeted diagnostic imaging has so far shown promising potential for a broad spectrum of cancers." (PMID 34858834, 2021). "Fibroblast activation protein (FAP) is one of the surface markers of cancer-associated fibroblasts (CAFs) and is closely related to the malignant characterization of CAFs." (PMID 34024061, 2021). "The stromal marker FAP is an emerging biomarker and has been linked to impaired prognosis and therapy resistance in several cancer." (PMID 34525114, 2021). "For stroma, the marker genes used were VWF, ENG, and CDH5 (for endothelial cells), DCN, ACTA2, and FAP (for cancer-associated fibroblasts), and PTPRC, CD4, and CD163 (for leukocytes)." (PMID 33810510, 2021). "Recently, fibroblast activation protein (FAP) expression in cancer-associated fibroblasts (CAFs) was evaluated as a possible target for PET imaging in oncology." (PMID 34681850, 2021). "Authors also showed that high expressions of FAP are associated with development of early metastases and worse cancer-specific survival." (PMID 33886004, 2021).
cancer (continued). "Non-inflamed tumors without TILs have been associated to activated β-catenin and PPAR-g, increased production of transforming growth factor β (TGF-β), presence of cancer associated fibroblasts expressing FAP protein and loss of PTEN." (PMID 34298868, 2021). "Fibroblast activation protein alpha (FAP) is a marker of cancer-associated fibroblast, which is also expressed in cancer epithelial cells." (PMID 34035230, 2021). "The first generation of radiolabeled FAP inhibitors (FAPI) is peptidomimetic quinoline derivatives that bind with high affinity to FAP expressed on cancer-associated fibroblasts (CAFs)." (PMID 34137945, 2021). "Histopathologic studies reported the prevalence of FAP-positive cancer-associated fibroblasts in ~90% of epithelial tumors." (PMID 34959613, 2021). "FAP is a marker expressed on cancer- associated fibroblasts (CAFs) in a majority of human malignancies." (PMID 34790207, 2021). "In parallel, a cancer-associated fibroblast (CAF) signature was anchored by FAP, CAV1, VIM, and additional genes." (PMID 34518533, 2021). "Contrarily, strategies to decrease inflammatory fibroblasts and FAP-positive fibroblasts are associated with decreased cancer growth and metastases." (PMID 34638432, 2021). "Fibroblast activation protein inhibitor (FAPI)-PET/CT is a novel imaging modality that uses inhibitors of FAP to visualize cancer associated fibroblasts (CAFs)." (PMID 33672893, 2021). "In this, so far the largest cohort of patients reported in literature, we therefore quantified FAP in cancer and stromal cells separately and analysed their association with survival." (PMID 34282761, 2021). "FAP-targeted radiotracers, recently introduced in cancer treatment, accumulate in Cancer-Associated Fibroblasts (CAFs)." (PMID 34830898, 2021). "Fibroblast activation protein (FAP), a membrane-anchored serine protease with dipeptidyl peptidase and endopeptidase activity, is overexpressed by cancer-associated fibroblasts (CAFs)." (PMID 34638433, 2021). "In histopathologic studies, FAP-positive cancer-associated fibroblasts were found in over 90% of epithelial tumors, which makes FAP a potential target for imaging and therapy in a large variety of malignancies." (PMID 34887714, 2021). "Fibroblast activation protein (FAP), overexpressed on cancer-associated fibroblasts (CAFs), is a novel target for molecular imaging of various tumors." (PMID 34858834, 2021). "Fibroblast activation protein-α (FAP) expression in cancer-associated fibroblasts (CAFs) has been associated with a higher risk of metastases and poor survival." (PMID 32428869, 2020). "FAP is a transmembrane serine protease that is highly expressed in the cancer-associated stromal cells of epithelial cancers." (PMID 33634030, 2020). "The expression of FAP in the cytoplasmic membrane is a hallmark of fibroblast activation in malignant tumours." (PMID 33207686, 2020). "Overexpression of FAP has been investigated and believed to be associated with prognosis in many diseases, especially in cancers." (PMID 33109151, 2020). "While there was significant heterogeneity between the donors, donors 1 and 3 showed upregulation of collagen and donors 1 and 2 upregulated FAP, suggesting that the pooled fibroblasts contain a heterogenous mix of cells with a cancer-associated phenotype." (PMID 33034643, 2020). "The interest in FAP as an immunotherapy target for these diverse cancers stems from its broad expression on cancer‐associated fibroblasts (CAFs), which are a major component of the stromal microenvironment of carcinomas." (PMID 33082953, 2020). "FAP was found to be expressed in CAFs that penetrated into the body of lymph nodes, which is a sign of fibroblast activation associated with cancer cell colonization." (PMID 32428869, 2020). "Clinically, the abundance of FAP+ CAFs is associated with poor prognosis of patients in several types of cancer." (PMID 33308315, 2020).
cancer (continued). "Fibroblast activation protein (FAP) are a surface marker of CAFs, and targeting FAP+ CAFs has been associated with overcoming the immunosuppressive cancer TME)." (PMID 33050151, 2020). "Over the past two decades, significant attention has gone to FAP in solid tumors, where it is mainly expressed on so-called cancer associated fibroblasts (CAFs)." (PMID 32728930, 2020). "While cancer associated fibroblasts have been targeted by fibroblast activation protein (FAP), it has been shown that the enzymatic inhibition of FAP does not always reduce CAFs' role in cancer progression." (PMID 31695805, 2019). "In contrast, the expressions of the cancer-associated proteins FAPα and CCL-2 in the CACs were more pronounced than the normal colon tissue." (PMID 31920487, 2019). "The carcinoma-associated fibroblasts (CAFs) are a central player in tumorigenesis and metastasis and the key characteristics of CAFs is the expression of FAP." (PMID 30809507, 2019). "A distinguishing feature of cancer-associated fibroblasts is expression of fibroblast activation protein (FAP), a type II membrane-bound glycoprotein belonging to the dipeptidyl peptidase 4 family." (PMID 29626120, 2018). "For example, fibroblast activation protein (FAP) is a transmembrane serine protease expressed in the cancer-associated stromal cells (CASCs) that emerged as a therapeutic target." (PMID 29682521, 2018). "Fibroblast activation protein (FAP) is a transmembrane serine protease with high expression on cancer-associated stromal cells (CASC) in epithelial cancers." (PMID 30031396, 2018). "FAP is overexpressed in many epithelial cancers including OC, and its expression is often associated with poor prognosis, cancer cell migration, invasion and immunosuppression." (PMID 30103384, 2018). "In the present study, we measured the plasma FAPα level in cancer patients and investigated the associations between circulating FAPα and patients’ clinical outcomes to evaluate the clinical value of plasma FAPα as diagnostic parameter in ESCC patients." (PMID 28415791, 2017). "Remarkably, FAP is highly expressed on cancer-associated fibroblasts in more than 90% of epithelial tumours." (PMID 28158223, 2017). "We also analyzed TCF4, which was found in the positive prognosis set, and FAP, a marker for cancer associated fibroblasts." (PMID 27809802, 2016). "Fibroblast activation protein (FAP) is a serine peptidase the expression of which in cancer-associated fibroblasts has been associated with higher risk of metastases and poor survival." (PMID 28033421, 2016). "Fourth, the studies not only identified a subgroup of different cancer types but also found that the pooled analyses indicated an association between FAP expression and many-sided clinical implications in solid tumors." (PMID 25775399, 2015). "In conclusion, this meta-analysis indicated that patients with FAP overexpression in solid tumors have a higher risk of cancer lymph node metastasis and worse prognosis than patients with low FAP expression." (PMID 25775399, 2015). "Silencing FAPα with short interfering RNA transfected using a lentiviral vector inhibited growth and resulted in cell cycle arrest at the G2 and S phases of cancer-associated fibroblasts in vitro." (PMID 25593080, 2015). "CD117 positive fibroblast-like stromal cells were further identified by mesenchymal stem/stromal cell (MSC) marker CD73 (NT5E) and cancer associated fibroblast (CAF) markers fibroblast activation protein (FAP) and α-smooth muscle actin (α-SMA)." (PMID 25380303, 2014). "Studies of FAP have reported that FAP expression is induced in fibroblasts associated with the stroma of malignant epithelial tumors and healing wounds." (PMID 19643020, 2009). "Finally, we showed that high stromal FAP is associated with shortened cancer‐specific and metastasis‐free survival, making it a superior IHC marker over epithelial FAP and stromal αSMA." (PMID 41410015, 2026).
cancer (continued). "FAP was utilized as a marker for cancer associated fibroblasts (CAFs) in subsequent analyses." (PMID 42052481, 2026). "Interestingly, it was observed that EBV-positive NPC cells would contribute to treatment resistance by inducing cancer-associated fibroblast-mediated immunosuppression through YAP1/FAPα signaling." (PMID 40160826, 2025). "Spatial analyses demonstrate that SPP1high macrophages colocalize with fibroblast activation protein (FAP)+ cancer-associated fibroblasts at the invasive front, forming a mesenchymal–myeloid circuit linked to desmoplasia, poor cytotoxic infiltration, and adverse outcome." (PMID 41567197, 2025). "For example, various TRT agents directed to fibroblast activation protein (FAP), which is expressed on cancer-associated fibroblasts (CAFs), have been developed and first clinical studies are being conducted to test its efficacy in cancer patients." (PMID 40281282, 2025). "In our study, we identified a lactate-based chemical barrier surrounding FAP+ cancer-associated fibroblasts (CAFs) within the LUAD microenvironment (TME), which may hinder the infiltration and function of CD8+ T cells." (PMID 40855046, 2025). "High levels of FAP have been associated with poor prognosis in various cancers." (PMID 41441395, 2025). "Although, the association of FAP with EMT in cancer has been studied." (PMID 40916258, 2025). "FAP is a type II transmembrane serine protease minimally expressed in normal adult tissues but strongly upregulated in fibrotic lesions, chronic inflammation, and cancer-associated fibroblasts." (PMID 41515504, 2025). "Single-cell and spatial analyses position SPP1high tumor-associated macrophages in tight contact with FAP+ cancer-associated fibroblasts at the invasive front, enriched for extracellular-matrix and TGF-β signaling; this configuration aligns with immune-excluded architecture and adverse outcome." (PMID 41567197, 2025). "The fibroblast activation protein (FAP), a type II trans-membrane serine protease, highly expressed in cancer-associated fibroblasts (CAFs) in more than 90% of epithelial tumors, has emerged as a valuable pan-cancer imaging target." (PMID 41258458, 2025). "Fibroblast activation protein (FAP)-binding radiopharmaceuticals have emerged as promising candidates for both diagnostic and therapeutic applications in oncology due to their selective targeting of cancer-associated fibroblasts (CAFs)." (PMID 41463267, 2025). "Confocal microscopy imaging revealed an elaborated cellular organization with FAP+ cells (a marker for cancer-associated fibroblast; CAF) forming a network in the center of MCTS, embedding clusters of CD31+ ECs and CD45+ monocytes where those cells appeared to form privileged contacts." (PMID 41310721, 2025). "Prior studies, including a meta-analysis which evaluated multiple cancer types, found that high expression of FAP may be associated with poor outcomes." (PMID 38575990, 2024). "In order to validate the correlation between VDR expression and immune infiltration, the expression of VDR and cell markers including FAP (cancer-associated fibroblast marker), CD68 (macrophage marker) and CD15 (neutrophil marker) in PTC tissues was examined by qRT-PCR." (PMID 38639057, 2024). "Additionally, MSC-2 shown high expression of cancer-associated fibroblast (CAFs) markers, including FAP, FN1, and CD44." (PMID 38281962, 2024). "Furthermore, recent studies have shown that FAP-targeted PET has yielded exceptional outcomes in detecting many types of cancers, including tumors usually linked to insignificant amounts of [18F]FDG uptake." (PMID 39061653, 2024). "While cancer-associated fibroblasts (CAFs) are often associated with high levels of FAP in cancer, multiple other cell types have been shown to have high FAP expression during various pathological conditions, including synovial fibroblasts, myo-fibroblasts, and chondrocytes." (PMID 38540158, 2024).